SLC25A43 (solute carrier family 25 member 43)
Tractability: Antibody: UniProt predicts a signal peptide or a membrane-spanning region.
Gene: Protein-coding gene on chromosome X (119,399,336 to 119,454,478, forward strand). Ensembl gene ENSG00000077713.
Subcellular location: Mitochondrion inner membrane
Subcellular location (Human Protein Atlas): Cytosol
Gene Ontology:
Molecular function: nucleobase-containing compound transmembrane transporter activity; organophosphate ester transmembrane transporter activity
Biological process: nucleobase-containing compound transport; organophosphate ester transport; transmembrane transport
Cellular component: mitochondrial inner membrane; mitochondrion
Homologues: Orthologues: chimpanzee SLC25A43 (99% identical), pig SLC25A43 (91% identical), guinea pig SLC25A43 (90% identical), dog SLC25A43 (89% identical), rabbit SLC25A43 (89% identical), mouse Slc25a43 (86% identical), rat Slc25a43 (82% identical), macaque SLC25A43 (72% identical), tropical clawed frog slc25a43 (63% identical), zebrafish slc25a43 (58% identical). Paralogues in human: SLC25A6 (25% identical), SLC25A4 (24% identical), SLC25A5 (24% identical), SLC25A31 (24% identical), SLC25A16 (20% identical), SLC25A13 (20% identical), SLC25A23 (19% identical), SLC25A25 (19% identical), SLC25A12 (18% identical), SLC25A30 (18% identical), SLC25A32 (18% identical), SLC25A40 (18% identical), and 37 more.
Diseases named in the same sentence as SLC25A43 in open-access papers:
SLC25A43 is named in the same sentence as 10 diseases in open-access papers, as found by Europe PMC text mining. Sharing a sentence is not in itself a finding about the gene and the disease. The quoted sentences say what the papers report.
breast carcinoma (7 papers, 2012 to 2024). "We previously demonstrated a common loss of the mitochondrial gene SLC25A43 in HER2-positive breast cancer." (PMID 23354756, 2013). "Higher CpG island methylation was also associated with lower age at diagnosis in HER2-positive breast cancer while deletion of SLC25A43 was found in tumors from patients with higher age at diagnosis." (PMID 22883974, 2012). "SLC25A43 KO in HER2-positive breast cancer cells (BT-474) increases proliferation and cell cycle progression via enhanced G1-to-S transition, suggesting a role for SLC25A43 as a regulator of the cell cycle through a putative mitochondrial checkpoint." (PMID 39795950, 2024). "By contrast, KD of SLC25A43 resulted in a significant reduction of cytotoxic effects by 16 nM paclitaxel in the two breast cancer cell lines MCF7 and BT-474 compared to siCtrl." (PMID 23354756, 2013). "We have also found that low protein expression of SLC25A43 significantly correlates with a lower S phase fraction in HER2-positive breast cancer." (PMID 23354756, 2013). "We noted that lower expression of SLC25A43 in the tumours correlated significantly with a lower S phase fraction in HER2-positive breast cancer." (PMID 23354756, 2013). "Our findings demonstrate that the mitochondrial protein SLC25A43 affects drug efficacy and cell cycle regulation following drug exposure in breast cancer cell lines." (PMID 23354756, 2013). "We have previously shown a common deletion of the gene SLC25A43 in human epidermal growth factor receptor 2 (HER2)-positive breast cancer." (PMID 23354756, 2013). "The common deletion found covering SLC25A43 indicates a possible role of this gene in HER2-positve breast cancer." (PMID 22883974, 2012). "This novel finding indicates a possible role of SLC25A43 in HER2-positive breast cancer through an altered mitochondrial function." (PMID 22883974, 2012). "We have found deletion in the SLC25A43 gene to be a common event in HER2-positive breast cancer as well as in other cancers." (PMID 22883974, 2012). "Our findings of deletion in the SLC25A43 gene together with varied SLC25A43 protein expression in HER2-positive breast cancers supports the role of altered mitochondrial function as a hallmark of cancer." (PMID 22883974, 2012). "For instance, methylation in the CpG islands of the SLC25A43 gene has been suggested to be a possible mechanism of gene silencing in breast cancer without loss of heterozygosity." (PMID 31612869, 2019). "In addition, the SLC25A43 protein expression was shown to be related to S-phase fraction in HER2-positive breast cancer." (PMID 22883974, 2012). "Our results indicate a possible role of SLC25A43 in HER2-positive breast cancer and support the hypothesis of altered mitochondrial function in cancer." (PMID 22883974, 2012). "Using siRNA, we investigated the effects of SLC25A43 knockdown (KD) on drug cytotoxicity in immortalised mammary epithelial cells, HER2-negative, and HER2-positive breast cancer cells after exposure to different drugs." (PMID 23354756, 2013). "We continued to verify the SLC25A43 deletion identified by whole-genome array, using a PCR-based LOH assay in 85 HER2-positive breast cancer cases." (PMID 22883974, 2012). "In this study, a common deletion of the SLC25A43 gene, located at Xq24, was revealed in HER2-positive breast cancer using whole-genome array." (PMID 22883974, 2012). "Research has found that the gene for the SLC25A43 mitochondrial transporter is commonly deleted in HER2+ breast cancer, as well as in other cancers, and altered SLC25A33 expression influences the proliferation of breast cancer cells." (PMID 32455902, 2020). "Following siRNA-mediated KD of SLC25A43, one non-malignant and two breast cancer cell lines were exposed to the anthracycline epirubicin or the taxane paclitaxel." (PMID 23354756, 2013).
breast carcinoma (continued). "Another possible mechanism for transcriptional silencing is increased methylation, and recent findings show higher methylation in the CpG island of the SLC25A43 gene in breast cancer in the absence of gene deletion." (PMID 22883974, 2012).
breast tumors (2 papers, 2012 to 2013). "We further showed that HER2-positive breast tumours with a lower expression of SLC25A43 also have a lower S phase fraction." (PMID 23354756, 2013). "To investigate presence of a possible second genetic alteration in the SLC25A43 gene, ensuring complete inactivation of a tumor suppressor gene, we screened 29 HER2-positive breast tumors for mutations." (PMID 22883974, 2012).
glioblastoma (1 paper, 2020). The most malignant astrocytic tumor (WHO grade IV). "Survival analysis revealed eight RBPs (PTRF, FNDC3B, SLC25A43, ZC3H12A, LRRFIP1, HSP90B1, HSPA5, and BNC2) are significantly associated with the survival of glioblastoma patients." (PMID 32272554, 2020).
hypospadias (1 paper, 2020). Hypospadias is the displacement of the urethral meatus on the ventrum of the penis. "And the deletion encompassing SLC25A43, LOC100303728, SLC25A5, CXorf56, UBE2A, NKRF, and SEPT6, is associated with hypospadias." (PMID 32515122, 2020).
overgrowth syndrome (1 paper, 2023). A group of syndromes caused by genetic birth defects that may lead to the development of malignancies. "Genetic investigations consisting of array-CGH and overgrowth syndrome panel showed a duplication of 140 kb in Xq24, encompassing SLC25A43 and the 5′ terminal of CXorf56, considered as likely benign as duplications of these regions are found in the control population." (PMID 36926521, 2023).
cancer (5 papers, 2012 to 2025). A tumor composed of atypical neoplastic, often pleomorphic cells that invade other tissues. "KD of SLC25A43 also reduced the inhibitory effect of trastuzumab on cell proliferation in the HER2-positive cancer cell line BT-474 (P<0.05), and the drug-induced G0/G1 block (P<0.05)." (PMID 23354756, 2013). "We found that KD of SLC25A43 resulted in a decreased cytotoxic effect of paclitaxel in the two cancer cell lines (P<0.05)." (PMID 23354756, 2013). "Deletion in SLC25A43 was also found to be present in other types of cancer in female patients, suggesting it to be a putative tumor suppressor gene." (PMID 22883974, 2012). "The LOH assay revealed presence of SLC25A43 deletion in HER2-positive (48%), HER2-negative (9%), cervical (42%) and lung (67%) cancers." (PMID 22883974, 2012). "Potentially, there could be further aspects of SLC25A43/AIC function, as the expression of the protein was found to be silenced or its gene damaged in different cancer cell lines." (PMID 40795994, 2025). "Since SLC25A43 has not been previously studied in relation to cancer we decided to further investigate this finding." (PMID 22883974, 2012).
tumor (3 papers, 2012 to 2024). "The immunostained tumor cells demonstrated a homogeneous expression of SLC25A43 within the tumor but the expression varied widely, spanning from non-existent to very high expression, between tumors." (PMID 22883974, 2012). "The high frequency of LOH found in SLC25A43 indicated a possible role as a tumor suppressor gene." (PMID 22883974, 2012). "The results indicate that SLC43A3, SLC25A43, SLC2A10 and SLC47A1 show sporadic expression in both tumour cells and TAMs." (PMID 38687049, 2024). "Interestingly, similar to the results obtained from bulk analysis, the single‐cell data showed a higher detection of SLC43A3, SLC2A10, SLC25A43, SLC7A7 and SLC47A1, which are highly expressed in tumour tissues, relative to SLC1A6 and SLC24A4, which are lowly expressed." (PMID 38687049, 2024). "As shown, of the various tumor pathological grades, the expression levels of SLC25A4 (P < 0.01), SLC25A11 (P < 0.0001), SLC25A24 (P < 0.01), SLC25A37 (P < 0.01), SLC25A42 (P < 0.01), SLC25A43 (P < 0.0001), SLC25A44 (P < 0.05) and SLC25A45 (P < 0.05) were significantly different." (PMID 36514121, 2022).
SLC25A43 also shares sentences with these, for which no sentence is quoted: lung carcinoma (1 paper); lymph node metastasis (1); metastasis (1).